ENSG00000265445 (novel transcript)
Synonyms: LOC124903931
Gene: Long non-coding RNA gene on chromosome 17 (15,260,958 to 15,312,026, forward strand). Ensembl gene ENSG00000265445.
Gene Ontology:
Molecular function: U4 snRNA binding
Biological process: formation of quadruple SL/U4/U5/U6 snRNP; spliceosomal tri-snRNP complex assembly
Cellular component: U4/U6 x U5 tri-snRNP complex; U6 snRNP